ARHGAP23 (Rho GTPase activating protein 23)
Description:
GTPase activator for the Rho-type GTPases by converting them to an inactive GDP-bound state.
Synonyms: KIAA1501
Tractability: Antibody: the Human Protein Atlas places it where antibodies can reach. PROTAC: UniProt records ubiquitination sites on it; ubiquitination databases record sites on it; its protein half-life has been measured.
Gene: Protein-coding gene on chromosome 17 (38,419,280 to 38,512,385, forward strand). Ensembl gene ENSG00000275832.
Subcellular location (Human Protein Atlas): Nucleoplasm; Plasma membrane; Cytosol
Pathways (Reactome):
Signal Transduction: RAC1 GTPase cycle; RHOA GTPase cycle
Gene Ontology:
Molecular function: GTPase activator activity
Biological process: regulation of small GTPase mediated signal transduction; signal transduction
Cellular component: extracellular exosome; cytosol
Genetic constraint (gnomAD): Loss-of-function variants: 33 observed, 106.68 expected, observed/expected ratio (o/e) 0.31, 90% interval 0.23 to 0.41. The upper end of that interval is the gene's LOEUF score, 0.41, which puts it in group 1 of 6, group 1 being the genes least tolerant of losing a copy. Missense variants: 1,665 observed, 1,742.5 expected, observed/expected ratio (o/e) 0.96, 90% interval 0.92 to 1. Synonymous variants: 750 observed, 724.45 expected, observed/expected ratio (o/e) 1.04, 90% interval 0.97 to 1.1.
Homologues: Orthologues: chimpanzee ARHGAP23 (99% identical), macaque ARHGAP23 (98% identical), pig ARHGAP23 (94% identical), mouse Arhgap23 (92% identical), rat Arhgap23 (92% identical), dog ARHGAP23 (88% identical), guinea pig ARHGAP23 (77% identical), rabbit ARHGAP23 (70% identical), tropical clawed frog arhgap23 (57% identical), zebrafish arhgap23a (45% identical), Drosophila melanogaster RhoGAP19D (20% identical), Caenorhabditis elegans pac-1 (18% identical). Paralogues in human: ARHGAP21 (41% identical).
Diseases named in the same sentence as ARHGAP23 in open-access papers:
ARHGAP23 is named in the same sentence as 7 diseases in open-access papers, as found by Europe PMC text mining. Sharing a sentence is not in itself a finding about the gene and the disease. The quoted sentences say what the papers report.
ovarian carcinoma (2 papers, 2020 to 2022). A malignant neoplasm originating from the surface ovarian epithelium. "We found that the expression of six genes (BCLAF1, FBLN1, ARHGAP23, STON2, UBQLN4, and ATP2B1) had a significant positive correlation with the survival rate of patients with ovarian cancer." (PMID 35978436, 2022). "In this study, we also showed that parent genes such as BCLAF1, FBLN1, ARHGAP23, STON2, UBQLN4, and ATP2B1 were significantly positively correlated with the survival rate of patients with ovarian cancer." (PMID 35978436, 2022).
alveolar soft part sarcoma (1 paper, 2025). An alveolar soft part sarcoma occurring in adults. "Diagnoses included ASPSCR1::TFE3 alveolar soft part sarcoma; WWTR1::CAMTA1 epithelioid hemangioendothelioma; INI-1 deficient epithelioid sarcoma; EWSR1::NR4A3 extra-skeletal myxoid chondrosarcoma; and low-grade ARHGAP23::FER spindle cell malignancy, a novel fusion-driven sarcoma." (PMID 39941809, 2025).
ARHGAP23 also shares sentences with these, for which no sentence is quoted: cancer (1 paper); epithelioid hemangioendothelioma (1); epithelioid sarcoma (1); sarcoma (1); soft part sarcoma (1).